NOD2 (nucleotide binding oligomerization domain containing 2)
Diseases named in the same sentence as NOD2 in open-access papers (continued):
Sharing a sentence is not in itself a finding about the gene and the disease.
colitis (127 papers, 2007 to 2025). Inflammation of the colon. "Regarding the molecular mechanisms underlying the suppression of DSS- and CpG-induced severe colitis by MDP activation of NOD2, OTUD5 expression was markedly increased in the colons of mice treated with MDP and CpG." (PMID 41155222, 2025). "Chronic Norovirus infection with strains such as MNoV_S99 and CR6 intensively exacerbated dextran sodium sulfate-induced colitis in wild-type animals, whereas NOD2-deficient animals were protected." (PMID 41020029, 2025). "Persistent controversy surrounds how NOD2 functions and how its variants drive colitis in both UC and CD." (PMID 40766554, 2025). "Resistance to TLR2-dependent colitis in NOD2-transgenic mice is associated with a diminished Th1 response." (PMID 39403381, 2024). "NOD2-deficient mice are more susceptible to bacterial OVA-specific colitis, when compared with NOD2-intact mice, and are characterized by the excessive accumulation of OVA-specific Th1 cells in the colonic lamina propria." (PMID 39403381, 2024). "Overall, our data indicate that loss of Nod2 signaling in lysozyme-expressing myeloid cells lowers carcinogenesis in the context of colitis." (PMID 37876927, 2023). "They observed that WT mice that were transiently co-housed with Nod2-KO mice, which are more susceptible to an induced colitis, developed an increased susceptibility to colitis." (PMID 36891315, 2023). "To determine if Nod2 plays an intrinsic role in the extravasation of these lysozyme-expressing CD102+ peritoneal macrophages to the colon in DSS-mediated colitis, we made Nod2-deficient competitive bone marrow (BM) chimeras (as described recently)." (PMID 37876927, 2023). "Mucispirillum schaedleri also induced colitis in a Nod2/Cybb deficient state, and is known to be associated with susceptibility to CD." (PMID 36910191, 2023). "NOD2 deficiency caused a pro-inflammatory environment because of dysbiosis and increased the risk of colitis and colitis-associated carcinogenesis, but this risk was reduced by transplanting normal microbiota." (PMID 37191444, 2023). "NOD2-mediated ecological imbalance made mice susceptible to colitis and CRC, whereas activating Gpr109a (the receptor of the symbiotic metabolite butyrate) inhibited colitis and carcinogenesis." (PMID 37009513, 2023). "The presence of NOD2 variants in 15% of the healthy population and the failure of NOD2-deficient mice to develop spontaneous colitis confirmed the multigenic nature of CD." (PMID 36012618, 2022). "Nod2 deficiency increases host susceptibility to colitis; this is associated with altered gut microbiota." (PMID 35954484, 2022). "For instance, it has been reported that alteration in the composition of gut microbiota caused by Nod2 deficiency gave rise to a reversible risk of colitis in mice, while reciprocal microbiota transplantation reduced disease risk." (PMID 34391464, 2021). "Mice deficient in NOD2 or RIPK2 are more susceptible to DSS or TNBS-induced colitis; however, the administration of RIPK2 inhibitors ameliorates chronic colonic inflammation." (PMID 33935757, 2021). "NOD2-deficient mice were susceptible to this unique type of colitis due to the excessive production of pro-inflammatory cytokines via TLR2 activation, because the mice deficient in both NOD2 and TLR2 were protected from colitis." (PMID 33935757, 2021). "An increase in the abundance of Clostridiales was also reported after infection with T. muris which protected against colitis in NOD2-/- deficient mice via a mechanism involving type 2 immunity." (PMID 33613446, 2020). "In experimental models, Nod2 deficiency was shown to promote the development of colitis and colorectal cancer." (PMID 33239685, 2020). "The study showed that the IBD-associated genes ATG16L1 and NOD2 most likely played an essential role in the beneficial immunomodulatory properties of Bacteroides fragilis, which protects mice from experimental colitis." (PMID 30849075, 2019).
colitis (continued). "The relative abundance of the Proteobacteria phylum was positively associated with ileal CD and colitis phenotypes, but negatively associated with NOD2 genotype." (PMID 30818349, 2019). "For example, knockout of Nod2 in mice predisposed them to colitis with lower levels of antimicrobial defensins and a higher bacterial load as compared with the control mice." (PMID 30828386, 2019). "In another study, however, Nod2 was shown to rather promote colitis, given that Nod2 deficient IL-10−/− mice were protected from large intestinal inflammation." (PMID 28752081, 2017). "It was later shown that NOD2 deficiency increases the susceptibility of mice to chemically induced colitis and colitis-associated carcinogenesis, and this is due to changes in the composition of gut bacterial communities and enhanced IL-6 production." (PMID 28632155, 2017). "In a mouse model, Nod2 deficiency led to an altered composition of the gut microbiota, predisposing mice to colitis." (PMID 26218526, 2015). "Compared to NOD2-deficient mice, NOD2xTLR2 double-deficient mice showed attenuated ovalbumin-induced colitis with impaired CD4+ T cell infiltration into the mucosa and reduced production of IFN-γ in MLN cells." (PMID 26067254, 2015). "Similar to CD patients, NOD2-deficient mice present dysbiosis with reduced ability to prevent intestinal colonization of pathogenic bacteria and enhanced sensitivity to colitis." (PMID 24886810, 2014). "NOD2-deficiency led to lower inflammation at the early stages of infection, but more severe colitis later, as a result of reduced clearance and higher bacterial abundance in the intestine." (PMID 24381573, 2013). "Transfer of either Nod2 deficient or wild type naive T cells induced colitis as indicated by the decreased weight gain, the higher colon pathology scores (pathology scores > 4) and the increased weight to length colon ratio observed in recipient mice." (PMID 24324812, 2013). "Wild-type mice that received disease-predisposing bacterial communities from NOD2 or RIPK2-deficient mice via co-housing or cross-fostering experiments suffered from increased susceptibility to DSS-induced colitis and colitis-associated carcinogenesis." (PMID 24409180, 2013). "To assess the potential contribution of the NLRs Nod1 and Nod2 in S. Typhimurium-induced intestinal inflammation, we tested the ability of wild-type S. Typhimurium to induce colitis in Rip2-deficient animals." (PMID 19662166, 2009). "Finally, the administration of RIPK2 siRNA protected NOD1- or NOD2-deficient mice from DSS-induced colitis, suggesting that RIPK2, activated by TLR2 and/or TLR4, plays a colitogenic role." (PMID 39403381, 2024). "Interestingly, the RIPK2-specific siRNA also diminished TNBS induced colitis in both NOD2-deficient and NOD1/NO2-double deficient mice, indicating the effect of RIPK2 on colitis was independent of either NOD1 or NOD2 signaling." (PMID 36959850, 2023). "One may infer that blood monocytes deficient for Nod2 may develop into inflammatory macrophages in the gut and lead to an increased inflammatory response in colitis for instance." (PMID 37415975, 2023). "While NOD2 can control the secretion of lysozyme P, lysozyme-P deficiency has been shown to decrease NOD2 signaling and to alter the microbiota resulting in the protection of the mice from colitis." (PMID 37876927, 2023). "CD patients with NOD2 mutations have a lower incidence of colitis than ileitis." (PMID 37876927, 2023). "Nod2 knockout reduces goblet cells in colonic mucosa and Muc2 secretion, resulting in an impaired intestinal epithelial barrier, greater bacterial translocation, imbalance of bacterial communities, and increasing the host’s susceptibility to colitis and CRC." (PMID 35954484, 2022).
colitis (continued). "Another observation that emerged from studies of the effect of BS-NOD2 over-expression was that under conditions where the TNBS-colitis induced was relatively mild, over-expression caused more severe colitis than observed in WT mice or in mice that over-express the CD-frameshift-NOD2." (PMID 36189261, 2022). "Moreover, mice deficient in NOD2 or RIPK2 displayed enhanced susceptibility to DSS-induced colitis due to intestinal dysbiosis." (PMID 33935757, 2021). "Additionally, the pathways of several genetic risk factors for IBD impair barrier function and lead to colitis, including the NOD2 (nucleotide-binding oligomerization domain containing 2) and autophagy pathways." (PMID 34075172, 2021). "Similar as in the case of TLRs, murine NLR knock-out models (Nod2, Nlrp3, Nlrp6, Nlrc4, caspase 1) with increased (albeit partly controversial) susceptibility in different colitis models point to NLRs as important host factors for the establishment of a protective gut microbiota." (PMID 33117398, 2020). "Two recent studies in mice demonstrated that NOD2 influences microbial resilience with prolonged alterations of the microbiota in Nod2-deficient mice after antibiotic treatment, in case of neonatally treated mice resulting in an increased susceptibility to colitis in adulthood." (PMID 33117398, 2020). "Furthermore, NOD2-deficient mice have exacerbated antigen-specific colitis that is dependent on TLR2 function." (PMID 31632962, 2019). "Depending on the applied in vivo model, Nod2 deficiency might either enhance or even prevent from colitis development." (PMID 28752081, 2017). "In a recent study in mice NOD2 deficiency was associated with changes in the structure of microbial communities that are detrimental to the host and lead to colitis and colitis-associated carcinogenesis, suggesting a role for NOD2 in modulating gut bacterial communities." (PMID 26830977, 2016). "Interestingly, the development of ovalbumin-induced colitis in mice deficient in nucleotide binding oligomerization domain 2 (NOD2), an intracellular pattern recognition receptor associated with increased susceptibility for CD, depends on TLR2-derived signals." (PMID 26067254, 2015). "In addition to CLRs, NLRs play a crucial role in colitis, as mice deficient for NOD2 exhibited more severe clinical symptoms than wild-type mice during the process of colitis." (PMID 25068517, 2014). "In addition, IL-10-deficient mice, which normally develop colitis, are protected from developing severe chronic colitis when a deletion of the NOD2 gene is also introduced into these mice." (PMID 25071778, 2014). "In addition, co-transfer of Nod2 deficient activated/memory CD4+CD45RBlow T cells prevented the induction of colitis and induced a development of Foxp3+ Treg cells comparable to the one observed after transfer of wild type T cells." (PMID 24324812, 2013). "By using the DSS-induced colitis model in NOD2-deficient zebrafish, the deficiency of NOD2 is observed to contribute to an impairment in the monocyte-macrophage lineage, while the mutation of NOD2 leads to the overexpression of collagen, all of which are associated with pathological fibrosis." (PMID 39095853, 2024). "Notably, severe bacterial OVA-specific colitis in NOD2-deficiency relies on the activation of TLR2 because mice double deficient in NOD2 and TLR2 display markedly less colonic inflammation and accumulation of OVA-specific Th1 cells in the colonic lamina propria." (PMID 39403381, 2024). "Furthermore, a study suggested that NOD2 could change the microbial microenvironment to promote the risk of colitis because microbiota in NOD2-deficient mice increased the opportunity of colonic mucosa injury." (PMID 37833958, 2023). "NOD2 signaling in intestinal DCs and macrophages has been shown to maintain intraepithelial lymphocytes, and the loss of NOD2 leads to a decrease in intestinal epithelial lymphocytes, which in turn predisposes mice to non- dextran sulfate sodium-induced colitis." (PMID 34881085, 2021).
colitis (continued). "Furthermore, a very elegant experiment in NOD2-deficient mice clearly demonstrated that genetic ablation of NOD2 is a triggering factor of dysbiosis, which is a critical risk component of colitis and colitis-associated carcinogenesis (CAC) in mice." (PMID 31412603, 2019). "Thus, TLR2-deficiency prevented the induction of T-cell-mediated colitis in NOD2−/− mice 36 and a recent study reported that NOD2 may down-regulate multiple TLR responses." (PMID 19950179, 2010). "Finally, we observed that Card15/Nod2 deficient mice are more susceptible to TNBS induced colitis." (PMID 17565376, 2007). "Suppression of DSS-induced colitis by NOD2 activation was accompanied by reduced production of IFN-α and CXCL10 by colonic lamina propria mononuclear cells upon in vitro stimulation with lipopolysaccharide and CpG." (PMID 41155222, 2025). "The siRNA-mediated knockdown of Otud5 resulted in the development of severe DSS-induced colitis even with MDP activation of NOD2 through the upregulation of colonic expression of IFN-α and CXCL10." (PMID 41155222, 2025). "In the DSS-induced colitis model, BI also activated the NOD2-like receptor signaling pathway, leading to increased NOD2 expression." (PMID 41036227, 2025). "Ablation of YOD1 attenuated the activation of NOD2-mediated signal transduction and functional outcomes in macrophages, leading to exacerbated colitis." (PMID 39333628, 2024). "In aggregate, these results demonstrate that OTUB2 promotes MDP‐induced innate immune responses in macrophages, indicating that OTUB2 ameliorates colitis by bolstering NOD2‐mediated protective effects in macrophages." (PMID 39358938, 2024). "Deletion of NOD2 decreased the severity of TNBS-colitis, an effect that is rescued by lymphocyte-predominant cells by adoptive transfer from ethanol-treated mice." (PMID 39000289, 2024). "In the present study, we found that NOD2-mediated protective responses in colitis were potentiated by YOD1, which inhibited the proteasomal degradation of RIPK2 by removing K48-linked polyubiquitin chains." (PMID 39333628, 2024). "Consistent with the protective role of NOD2 signaling in colitis, deficiency of RIPK2 significantly exacerbated colitis in Yod1+/+ mice." (PMID 39333628, 2024). "MDP-mediated activation of NOD2 inhibits the DSS- or TNBS-induced colitis via suppression of NF-κB-dependent proinflammatory cytokine responses." (PMID 39403381, 2024). "In summary, this study shows that YOD1 mediates optimal NOD2 signal transduction in macrophages and thereby ameliorates experimental colitis." (PMID 39333628, 2024). "Collectively, the findings of this study identified YOD1 as a novel regulator of NOD2 signaling and experimental colitis, and highlight the potential of YOD1 as a beneficial therapeutic target for IBD." (PMID 39333628, 2024). "Prior systemic injection of MDP protects NOD2-intact mice from TNBS-induced colitis, whose effects are accompanied by diminished NF-κB activation and proinflammatory cytokine responses against multiple TLR ligands in the colonic lamina propria immune cells." (PMID 39403381, 2024). "Of interest, it has been recently indicated that NOD2 activation in hematopoietic cells protected mice from TLR9-induced exacerbation of DSS-induced colitis by downregulating IFNα responses." (PMID 39346917, 2024). "Thirdly, research reported that L. acidophilus activates the production of IL-17 and IL-22 of ILC3 and then improves colitis in a nucleotide binding oligomerization domain containing 2 (NOD2)-dependent manner." (PMID 39497434, 2024). "Taken together, these results demonstrate that YOD1 is indispensable for NOD2-induced protective effects in experimental colitis." (PMID 39333628, 2024). "Taken together, our data suggest that bacterial sensing by intestinal myeloid cells via NOD2 promotes inflammation during acute colitis and impairs the intestinal repair phase after acute colitis." (PMID 37876927, 2023).
colitis (continued). "And Lactobacillus salivarius Ls33-purified peptidoglycan induces the dendritic cell to secrete IL-10 through a NOD2-dependent manner to relieve colitis." (PMID 37114045, 2023). "Here the authors identify an uncharacterized secreted enzyme named LPH from multiple probiotic Lactobacillus strains, which protects female mice from chemically induced colitis and colorectal cancer via NOD2 signalling." (PMID 37286542, 2023). "Supplementation of dl-endopeptidases or dl-endopeptidase-producing bacteria strains and a synthetic lipophilic analog of MDP protected against colitis in mice by restoring the NOD2 pathway." (PMID 37191444, 2023). "dl-Endopeptidase, a Firmicutes peptidoglycan remodeling enzyme, increased NOD2 levels in the gut and impacted colitis outcomes." (PMID 37191444, 2023). "Important risk variants in murine models as well as IBD patients impair P cell function, leading to colitis; notably, the autophagy gene ATG16L1 and NOD2 mutations, with disturbed secretory P cells, result in antibacterial autophagy defects." (PMID 37686376, 2023). "We employed the Nod2 knockout (Nod2−/−) mice and found that LPH lost the ability to protect Nod2−/− mice against TNBS-induced colitis." (PMID 37286542, 2023). "NOD2 signaling promotes hyper-reactive macrophages and colitis in IL10-deficient mice, and NOD2 deficiency in IL10−/− mice leads to a significant improvement in chronic colitis." (PMID 36814903, 2023). "Altogether, these studies suggest that NOD2 pathway is an important anti-colitis mechanism of traditional probiotics." (PMID 37286542, 2023). "The global protective role of NOD2 in gut inflammation and colitis has been evaluated in various studies." (PMID 37876927, 2023). "NOD2 deletion ameliorated colitis severity in IL-10-/- mice and this effect was dependent on the gut microbiota composition." (PMID 37876927, 2023). "In the present study, the use of the LysMcre knock-in/knock-out mice led us to unveil that specific ablation of Nod2 expression in myeloid cells renders mice more resistant to colitis and CAC in a lysozyme-dependent manner." (PMID 37876927, 2023). "Different active site mutants of LPH in combination with Nod2 knockout female mice confirm that LPH exerts anti-colitis effects through MDP-NOD2 signaling." (PMID 37286542, 2023). "The role of NOD2 was studied in a setting of Dextran Sodium Sulfate (DSS)-induced colitis and in azoxymethane (AOM)/DSS model." (PMID 37876927, 2023). "The mechanism of NOD2 in intestinal epithelium in the development of colitis still needs to be explored to lay the foundation for MDP-based postbiotics in IBD treatment." (PMID 36506547, 2022). "Using body weight loss as a criterion of inflammation, we found that mice administered a WT NOD2 vector were protected from the development of TNBS-colitis whereas mice administered a CD-frameshift NOD2 (FS987), or empty vector were not protected." (PMID 36189261, 2022). "In NOD2 related signaling, Pellino3 exerts a protective function via NOD2 in chemical drugs induced models of colitis." (PMID 35197966, 2022). "This caveat, however, is less applicable to the responses of heterozygous mice since these mice exhibited colitis as severe as that in the homozygous mice yet expressed substantial amounts of unmutated NOD2." (PMID 36189261, 2022). "Complementary studies of the ability of over-expressed NOD2 to protect mice from TNBS-colitis were then conducted in transgenic mice expressing WT-NOD2 or BS-NOD2 transgenes containing a R314W mutation." (PMID 36189261, 2022). "Supportive of this finding, macrophages of Nod2 knockout murine models with colitis showed increased production of IL-1β." (PMID 36203564, 2022). "Likewise, based on the determinative role of NOD2 (Nucleotide-binding oligomerization domain-containing protein 2) in the regulation of intestinal microbiota composition, gut dysbiosis following NOD2 deficiency augmented the risk of colitis and colitis-associated colorectal cancer in mice." (PMID 35794566, 2022).